CCR2 (C-C motif chemokine receptor 2)
Diseases named in the same sentence as CCR2 in open-access papers (continued):
Sharing a sentence is not in itself a finding about the gene and the disease.
myelofibrosis (1 paper, 2024). A partial or complete replacement of the bone marrow stroma by fibrous tissue. "A recent investigation revealed that among the MPN cohort, the proportion of CCR2+ cells is significantly associated with the severity of myelofibrosis in patients, and CCR2 expression on CD34+ cells correlates with higher-risk classifications in MF and the presence of circulating blast cells." (PMID 39850880, 2024).
nasal polyps (1 paper, 2024). "Our study suggests that Methanobrevibacter may contribute to an increased risk of nasal polyps by affecting the levels of CCR2 on CD62L+ myeloid dendritic cells and CD3 on CD4 regulatory T cells." (PMID 39346904, 2024). "Methanobrevibacter inhibited CCR2 on CD62L+ myeloid dendritic cells, a protective factor against nasal polyps, or mediated elevated levels of CD3 on CD4 regulatory T cells, which ultimately led to an increased risk of polyps." (PMID 39346904, 2024).
neuritis (1 paper, 2026). A neuropathy arising from inflammation of one or more nerves. "Moreover, CCL2 can attract CCR2‐positive macrophages to the immune microenvironment of neuritis, where they promote neural invasion by activating RET signaling in cancer cells." (PMID 41556039, 2026).
obstructive sleep apnea (1 paper, 2014). "Intermittent hypoxia, the hallmark of obstructive sleep apnea, was proved to increase the CCR2 gene expression and the chemotaxic ability of monocytes toward MCP-1." (PMID 25411969, 2014). "Since intermittent hypoxia is the hallmark of obstructive sleep apnea, we further examined the effect of intermittent hypoxia on the CCR2 expression in monocytes both at the mRNA and protein levels." (PMID 25411969, 2014).
ovarian tumors (1 paper, 2021). "CCR2 plays a certain role in the tumorigenesis of ovarian tumors through immune cells and related regulatory responses in the microenvironment, which is also worthwhile to explore in the future." (PMID 33921111, 2021).
Pain (1 paper, 2012). An unpleasant sensory and emotional experience associated with actual or potential tissue damage, or described in terms of such damage. "As the significant upregulation of CCL2 and CCR2 was observed from day 3 after IAMNT, we speculate CCL2-CCR2 signaling may be involved the maintenance rather than the development of the trigeminal neuropathic pain." (PMID 22721162, 2012).
pancreatic neuroendocrine cancers (1 paper, 2013). "CSF-1/CSF-1R and CCL2 (MCP-1)/CCR2 signaling in murine breast and pancreatic neuroendocrine cancers induces TAM recruitment and a pro-tumorigenic M2-like phenotype." (PMID 23372702, 2013).
Peri-Implantitis (1 paper, 2024). An inflammatory process with loss of supporting bone in the tissues surrounding functioning DENTAL IMPLANTS. "Additionally, in periodontal tissues affected by peri-implantitis, the elimination of CCR2 resulted in reduced production of pro-inflammatory cytokines and impaired osteoclast activity, suppressing peri-implant inflammation and bone loss." (PMID 38974387, 2024).
plague (1 paper, 2013). Plague is a severe bacterial infection caused by the gram-negative bacterium Yersinia pestis. "We recently showed that C57BL/6 Ccr2−/− mice develop pneumonic plague with similar kinetics as wild type mice suggesting that CCR2+ cells may play only a minor role during WT infection." (PMID 23633954, 2013).
pneumococcal pneumonia (1 paper, 2022). A febrile disease caused by STREPTOCOCCUS PNEUMONIAE. "To determine whether CCR2-mediated monocyte recruitment was essential to the remodeled AM phenotype, we examined WT and CCR2–/– mice that recovered from prior pneumococcal pneumonias." (PMID 35133985, 2022). "Beyond CCR2 independence, our data demonstrate that both the initial embryonic origin AM and the more newly recruited monocyte-derived AM subsets undergo similar remodeling after recovery from pneumococcal pneumonia." (PMID 35133985, 2022).
polyneuropathy (1 paper, 2024). A disease or disorder affecting more than one nerve. "However, the polyneuropathy was not prevented by knocking out CCR2 in this model." (PMID 39628475, 2024).
primary immunodeficiency (1 paper, 2023). "Meanwhile, KEGG gene sets found that CCR2 was primarily enriched in the chemokine signaling pathway, the T cell receptor signaling pathway, Fc gamma R mediated phagocytosis, the Toll-like receptor signaling pathway, and primary immunodeficiency." (PMID 37760894, 2023).
primary sclerosing cholangitis (1 paper, 2021). "In contrast, C-C chemokine receptor type 2 (CCR2)-mediated recruitment of monocyte-derived macrophages in a murine model of primary sclerosing cholangitis has been implicated in the mechanism of liver injury and fibrosis." (PMID 33411796, 2021).
psoriatic arthritis (1 paper, 2021). Joint inflammation associated with psoriasis. "Previous studies indicated that CCR2 induced the accumulation of γδ T cells in inflammatory skin caused by psoriatic arthritis and those cells mainly exhibited the CCR6--CCR2+ phenotype." (PMID 33653377, 2021).
pulmonary sarcoidosis (1 paper, 2011). Sarcoidosis affecting the lung parenchyma. "However, persistent expression of CCL2 interacting with CCR2 can lead to the fibroplasia of late stages of pulmonary sarcoidosis." (PMID 21463523, 2011). "Plausibly, this CCR2/CCL2 axis can recruit mononuclear cells that form and expand the granulomatous disease during early inflammatory stages of pulmonary sarcoidosis." (PMID 21463523, 2011).
relapsing-remitting MS (1 paper, 2019). "As such, a CCR2 antagonist, MK-0812, had entered a phase 2 clinical trial for treating patients with relapsing-remitting MS (NCT00239655)." (PMID 31849962, 2019).
Respiratory tract infection (1 paper, 2019). An infection of the upper or lower respiratory tract. "During respiratory tract infections, the early expression of IL-1α by CCR2+ monocytes precedes the recruitment of neutrophils to the lung." (PMID 31425553, 2019).
retinal (1 paper, 2011). "Previous studies have shown that mice with deletions of certain chemokine such as ccl2 or chemokine receptors including ccr2 or cx3cr1 or both ccl2/cx3cr1 genes develop retinal lesions akin to human AMD." (PMID 21850237, 2011). "Using the same mice, in this study, we observed discrete patches of whitish retinal lesions in 40% of CCL2 KO mice and 24% of CCR2 KO mice (>18 month)." (PMID 21850237, 2011).
rib fracture (1 paper, 2014). A traumatic or pathologic injury to the rib in which the continuity of the rib is broken. "Next, to elucidate whether the MCP-1/CCR2 axis is involved during the early phase of fracture healing, we continuously administered RS102895 before (pre-treatment) or after (post-treatment) rib fracture." (PMID 25133509, 2014).
schwannoma (1 paper, 2020). A benign, usually encapsulated slow growing tumor composed of Schwann cells. "On the other hand, 10 nM and 100 nM fMLF stimulation upregulated Fpr2 in RT4 schwannoma cells, and also increased levels of chemokine receptor CCR2 and CXCR4 as well as PKCβ." (PMID 33322305, 2020). "From these results using an in vitro RT4 schwannoma model, we can assume that chemokine receptors CCR2 and CXCR4 may serve as co-receptors of Fpr2 when Schwann cells of the distal nerve stump are stimulated with formylated peptides released from injured axons." (PMID 33322305, 2020).
scoliosis (1 paper, 2025). A congenital or acquired spinal deformity characterized by lateral curvature of the spine. "FSD1L shared the same variant with CCR2 on CD14− CD16− which could increase the risk of scoliosis." (PMID 40177401, 2025). "In our MR analysis, we noted that the increased expression of CX3CR1 on CD14− CD16−, which shared the same variant with SERPINH1, and CCR2 on CD14− CD16−, which shared the same variant with FSD1L, was associated with an elevated risk of scoliosis." (PMID 40177401, 2025). "Basophil %CD33dim HLA DR− CD66b− (p-value, <0.001; OR, 1.203; 95%CI, 1.08−1.34), CX3CR1 on CD14− CD16− (p-value, 0.006; OR, 1.297; 95%CI, 1.078−1.562), and CCR2 on CD14− CD16− (p-value, 0.002; OR, 1.478; 95%CI, 1.157−1.889) could increase the risk of scoliosis." (PMID 40177401, 2025).
sialadenitis (1 paper, 2007). Sialadenitis is an infection of the salivary glands. "In sialadenitis, only MRL/lpr mice that had undergone transfer of 5 × 105 CCR2-Treg cells showed significantly lower levels of periductal mononuclear cell infiltration and parenchymal destruction compared with the other four groups." (PMID 17284325, 2007).
sickle cell disease (1 paper, 2012). Sickle cell anemias are chronic hemolytic diseases that may induce three types of acute accidents: severe anemia, severe bacterial infections, and ischemic vasoocclusive accidents (VOA) caused by sickle-shaped red blood cells obstructing small blood vessels and capillaries. "In both subjects with sickle cell disease and the mouse model, fibrocytes expressed a hierarchy of chemokine receptors, with CXCR4 expressed on most fibrocytes, and CCR2 and CCR7 expressed on a smaller subset of cells." (PMID 22442712, 2012).
squamous intraepithelial lesions (1 paper, 2021). "Interestingly, the CCL2 receptor, CCR2, prevented the progression from squamous intraepithelial lesions to invasive cervical carcinoma if carrying the polymorphism CCR2-64I." (PMID 34833360, 2021). "Additional work of the same group showed that CCR2-64I polymorphism might contribute to the establishment of high-grade squamous intraepithelial lesions through the disruption of the naturally fragile immune response that is directed towards human papillomavirus infection." (PMID 34833360, 2021).
ST Elevation Myocardial Infarction (1 paper, 2022). A myocardial infarction that produces elevation in the ST segments of the ECG. "A study, examining the expressions of CCL2 and CCR2 in the plasma, found that in 80 STEMI (ST-Elevation Myocardial Infarction) patients with platelet high response, patients had higher expressions of CCL2 or CCR2 than those patients with a platelet normal response." (PMID 35749425, 2022).
stenosis (1 paper, 2021). "Both CCR2 and its cognate antigen CCL2/MCP-1 are linked to human arterial stenosis and genetic and pharmacologic disruption of MCP-1/CCR2 signaling effectively suppresses arterial remodeling in animal models." (PMID 34934133, 2021).
Stillbirth (1 paper, 2024). Death of the fetus in utero after at least 22 weeks of gestation. "Here, we infected pregnant CCR2-deficient mice with T. gondii, resulting in stillbirth, embryonic resorption, fetal morphological abnormalities, and preterm delivery at significantly higher rates than those in pregnant wild-type (WT) mice." (PMID 39051675, 2024). "Our study revealed that pregnant CCR2-deficient mice infected with T. gondii showed significantly higher rates of fetal stillbirth, embryonic resorption, fetal morphological abnormalities, and preterm delivery than those in pregnant WT mice." (PMID 39051675, 2024). "Furthermore, transferring inflammatory monocytes collected from WT mice to pregnant CCR2-deficient mice suppressed fetal stillbirth, embryonic resorption, and fetal morphological abnormalities." (PMID 39051675, 2024).
tauopathy (1 paper, 2021). Neurodegenerative disorders involving deposition of abnormal tau protein isoforms (tau proteins) in neurons and glial cells in the brain. "The CCR2/CCL2 axis is required to modify pathology using PD-L1 blockade in a mouse model of tauopathy." (PMID 34172073, 2021). "To address the role of the CCR2 axis, we administered PD-L1 immunotherapy in a mouse model of tauopathy, and found that a single systemic injection of anti-PD-L1 antibody (αPD-L1) led to upregulation of CCR2+ monocytes and Tregs in the peripheral blood." (PMID 34172073, 2021). "Here, we hypothesized that the C-C chemokine receptor 2 (CCR2)/CCL2 axis might be involved in the therapeutic effect in tauopathy, by facilitating recruitment of CCR2+ monocytes." (PMID 34172073, 2021). "Here, we hypothesized that the brain-immune communication pathway that is needed to be activated to combat tauopathy involves monocyte mobilization via the C-C chemokine receptor 2 (CCR2)/CCL2 axis, and additional immune cells, such as CD4+ T cells, including FOXP3+ regulatory CD4+ T cells." (PMID 34172073, 2021). "Altogether, our results suggest that the CCR2/CCL2 axis is an important player in brain-immune communication, needed for modifying tauopathy." (PMID 34172073, 2021).
thymoma (1 paper, 2026). A neoplasm arising from the epithelial cells of the thymus. "Thus, CCR2 on CD14+ CD16+ monocytes emerges as a critical driver of the transition from benign to malignant thymomas." (PMID 41497137, 2026). "Our study revealed that the expression of CCR2 on CD14+ CD16+ monocytes promotes both benign and malignant thymomas." (PMID 41497137, 2026).
urinary obstruction (1 paper, 2024). "This resulted in the amelioration of urinary dysfunction in Ccr2-KO mice, but a shared increase in bladder weight indicating similar levels of urinary obstruction reached only after three months." (PMID 38977751, 2024).
visceral leishmaniasis (1 paper, 2019). A severe form of leishmaniasis characterized by irregular bouts of fever, substantial weight loss, swelling of the spleen and liver, and anemia (which may be serious). "In a visceral leishmaniasis study using L. donovani, Ly6Chi inflammatory monocytes formed an important niche for parasite survival, and blocking their recruitment to the liver and spleen using CCR2 antagonists reduced bacterial burdens." (PMID 32039054, 2019).
tumor (1,179 papers, 2008 to 2026). "For instance, targeting the CCL2/CCR2 signaling pathway can reprogram tumor-associated macrophages (TAMs), thereby enhancing immune cell infiltration and antitumor immune responses." (PMID 41601632, 2026). "Evaluation of multiple immunocompetent syngeneic tumor-bearing mouse models demonstrated that the baseline levels of CCR2-expressing intratumoral mMDSCs were positively associated with antitumor response to mTAK-500 (R2 = 0.87; P = 0.006)." (PMID 39918395, 2025). "At the gene level, cancer-associated variants were infrequent, with the most variable gene, CCR2, bearing cancer-associated variants in only ~0.3% of tumor samples." (PMID 40273912, 2025). "Androgen blockade or AR loss increases CCL2 production from both tumor cells and stromal compartments, enhancing CCR2+ monocyte influx and downstream STAT signaling, which subsequently accelerates tumor progression and dissemination." (PMID 41488638, 2025). "PHGDH deficiency reduces CCR2 expression in TAMs, likely through the mTORC1 signaling pathway, which impairs macrophage migration toward tumor cells." (PMID 39905317, 2025). "We found that iIRE induces a CCR2+ tumor-associated macrophage (CCR2+ TAM)–mediated immunosuppressive microenvironment in residual tumors." (PMID 40700478, 2025). "The analysis identified the most prominent and significantly altered cell clusters as Tumor-associated macrophages (TAMs) (Clusters 1, 2, and 3), characterized using macrophage markers such as Adgre1 (F4/80), Apoe, Lyz2, Ccr2, and Ccl2." (PMID 41321310, 2025). "MC38 and LLC1 Ccl2-deficient tumor cells showed reduced lung metastasis in both Ccr1- and Ccr2-deficient mice when compared to wild-type mice." (PMID 39566333, 2025). "In their models, CCR2 deficiency was associated with a reduction in the presence of immunosuppressive myeloid-derived suppressor cells (MDSCs) within the tumor, while their numbers increased in the bone marrow." (PMID 40867316, 2025). "Strategies to overcome resistance involve combining ICIs with natural compounds, such as silibinin, to enhance immunogenicity and targeting stromal interactions, e.g., the CCL2/CCR2 axis and decreased tumor-associated macrophage (TAM) recruitment." (PMID 40650040, 2025). "Shu (2018) showed that the expression of miR-150-5p in the THP-1 line monocytes by inhibiting Notch3 caused a decrease in the expression of the CCR2 on tumor-associated monocyte cells." (PMID 40822140, 2025). "While these results are promising, more dedicated preclinical and clinical studies are needed to evaluate the therapeutic potential of CCR2 inhibitors specifically in tumor patients, particularly those with F. nucleatum-associated or adipocyte-rich tumors." (PMID 41276817, 2025). "CCL2/CCR2 recruits inflammatory monocytes that differentiate into tumor-associated macrophages (TAMs), often assuming immunosuppressive, pro-angiogenic phenotypes that blunt cytotoxic T-cell control." (PMID 41440526, 2025). "It was demonstrated that the CCL2/CCR2 axis is associated with tumor aggressiveness in DE-DLBCL by increasing M2 polarization rates, making it a potential therapeutic target." (PMID 40426926, 2025). "CCR2+ monocytes in the bone marrow constitute the major precursor pool for tumor-associated macrophages (TAMs), and their differentiation into this specialized population is markedly intensified during tumor progression." (PMID 41320679, 2025). "Consistently, Il1b and Il1a expressions were significantly decreased in the tumor tissue of CCR2-deficient mice compared to WT mice, further corroborating that monocytes and monocyte-derived macrophages are the major source of IL-1 ligands in the colon TME." (PMID 39030280, 2024). "CCR2 expression on monocytes is critical for the recruitment of tumor-associated macrophages, inflammation, cancer growth, and metastasis." (PMID 38870262, 2024). "Reduced CCR2 expression in muscle is associated with decreased adverse effects from tumor growth in mice." (PMID 38973385, 2024).